KRABD3 (KRAB domain containing 3)
Synonyms: KIAA1862; KRBA1
Tractability: PROTAC: ubiquitination databases record sites on it.
Gene: Protein-coding gene on chromosome 7 (149,714,781 to 149,734,575, forward strand). Ensembl gene ENSG00000133619.
Subcellular location (Human Protein Atlas): Nucleoplasm; Cytosol
Pathways (Reactome):
Gene expression (Transcription): Generic Transcription Pathway
Genetic constraint (gnomAD): Loss-of-function variants: 91 observed, 89.33 expected, observed/expected ratio (o/e) 1.02, 90% interval 0.86 to 1.21. The upper end of that interval is the gene's LOEUF score, 1.21, which puts it in group 5 of 6, group 1 being the genes least tolerant of losing a copy. Missense variants: 1,386 observed, 1,281.7 expected, observed/expected ratio (o/e) 1.08, 90% interval 1.03 to 1.13. Synonymous variants: 570 observed, 534.73 expected, observed/expected ratio (o/e) 1.07, 90% interval 0.99 to 1.14.
Homologues: Orthologues: chimpanzee KRBA1 (98% identical), chimpanzee KRBA1 (94% identical), macaque KRBA1 (93% identical), rabbit KRBA1 (70% identical), dog KRBA1 (61% identical), mouse Krba1 (60% identical), rat Krba1 (59% identical), pig KRBA1 (58% identical), guinea pig KRBA1 (51% identical).
Diseases named in the same sentence as KRABD3 in open-access papers:
KRABD3 is named in the same sentence as 1 disease in open-access papers, as found by Europe PMC text mining. Sharing a sentence is not in itself a finding about the gene and the disease.
KRABD3 shares sentences with these, for which no sentence is quoted: tumor (1 paper).